ZDHHC15 (zDHHC palmitoyltransferase 15)
Diseases named in the same sentence as ZDHHC15 in open-access papers (continued):
Sharing a sentence is not in itself a finding about the gene and the disease.
Intellectual disability (2 papers, 2019 to 2021). "Loss-of-function variants in several zDHHCs, including zDHHC15, have been identified in patients with intellectual disabilities; however, the function of zDHHC15 in the brain has not been well studied." (PMID 31189538, 2019).
malignant glioma (2 papers, 2023). A grade III or grade IV glioma arising from the central nervous system. "Furthermore, high ZDHHC15 expression was more prevalent in malignant glioma subtypes, including recurrence, IDH wild-type, and 1p/19q non-codeletion, which are considered markers of a poor prognosis." (PMID 37161425, 2023).
Anxiety (1 paper, 2021). Intense feelings of nervousness, tension, or panic often arise in response to interpersonal stresses. "Zdhhc15-KO mice were evaluated for anxiety-related behaviors and social interactions." (PMID 33462194, 2021).
Asperger syndrome (1 paper, 2014). "Of these, OPHN1, IGBP1, DLG3, NLGN3, and ZDHHC15 are associated with mental retardation or Asperger syndrome phenotypes." (PMID 24778889, 2014).
autism (1 paper, 2023). Persistent deficits in social interaction and communication and interaction as well as a markedly restricted repertoire of activity and interest as well as repetitive patterns of behavior. "Additionally, ZDHHC15 gene mutation has been linked to hypotonic cerebral palsy, autism, epilepsy, and intellectual disabilit, suggesting that ZDHHC15 plays an essential role in the central nervous system and is associated with psychiatric disorders." (PMID 37161425, 2023).
autoimmune disease (1 paper, 2022). A disorder resulting from loss of function or tissue destruction of an organ or multiple organs, arising from humoral or cellular immune responses of the individual to their own tissue constituents. "The further development of more potent and selective inhibitors of zDHHC15 could have utility for the treatment of induced autoimmune disease involving the constitutive activation of STING (stimulator of interferon genes)." (PMID 36087837, 2022).
congenital heart anomaly (1 paper, 2019). "The third VOUS is a Xq13.3 duplication in a fetus with congenital heart anomaly, where part of ZDHHC15 gene (OMIM*300576) is duplicated." (PMID 31004418, 2019).
ovarian carcinoma (1 paper, 2025). A malignant neoplasm originating from the surface ovarian epithelium. "IHC staining revealed that high expression of ZDHHC15 was associated with high‐grade ovarian cancer, and significantly correlated with distal metastasis." (PMID 39686664, 2025). "To assess the clinical significance of ZDHHC15 in cancer development, we evaluated the overall survival of patients with breast or ovarian cancers in relation to ZDHHC15 expression in The Cancer Genome Atlas (TCGA) datasets." (PMID 39686664, 2025). "Of important, ZDHHC15 expression is critical for dietary PA‐promoted metastasis in breast and ovarian cancer models." (PMID 39686664, 2025). "Together, our data indicate that ZDHHC15 expression and its palmitoyltransferase activity are critical for metastasis in breast and ovarian cancers." (PMID 39686664, 2025). "Collectively, our study has established an oncogenic role of ZDHHC15 in breast and ovarian cancers." (PMID 39686664, 2025). "In the current study, the clinical relevance of ZDHHC15 in breast and ovarian cancers is examined." (PMID 39686664, 2025). "This study uncovers that dietary palmitic acid (PA) acts as a potent inducer of YAP signaling in metastasis in breast and ovarian cancers, which is achieved by increasing the expression of palmitoyltransferase ZDHHC15, which in turn palmitoylates KIBRA and forms a feedback loop with YAP." (PMID 39686664, 2025). "In addition, we analyzed ZDHHC15 expression in ovarian cancer of different grades in a cohort of 65 patients." (PMID 39686664, 2025). "Furthermore, IHC analysis revealed a markedly increased staining for KIBRA in tumor sections from animals receiving breast and ovarian cancer cells with ZDHHC15 silencing." (PMID 39686664, 2025). "In addition, elevated ZDHHC15 expression positively correlated with high‐grade ovarian cancer." (PMID 39686664, 2025). "A significantly positive correlation between ZDHHC15 and YAP expression was noted in tissue samples from ovarian cancer patients." (PMID 39686664, 2025). "Given the lack of traditionally druggable molecules in Hippo/YAP pathway, our data suggest an alternative way of targeting YAP, i.e., targeting ZDHHC15, at least in YAP‐ driven breast and ovarian cancers." (PMID 39686664, 2025). "Supporting these findings, we found a strong positive correlation between ZDHHC15 and TEAD1 expression in breast, liver, and ovarian cancers by mining the RNA‐sequencing data across different cancer types in The Cancer Genome Atlas (TCGA)." (PMID 39686664, 2025). "Importantly, as we observed that the ZDHHC15‐YAP feedback loop is functional in both breast and ovarian cancer cells, this strongly suggests that the loop might be conserved across multiple cancer cell types." (PMID 39686664, 2025).
Primary amenorrhea (1 paper, 2021). "Intriguingly, another female patient with a different X-autosome translocation interrupting ZDHHC15 expression was reported to only have primary amenorrhea without cognitive impairment." (PMID 33462194, 2021).
cancer (5 papers, 2021 to 2025). A tumor composed of atypical neoplastic, often pleomorphic cells that invade other tissues. "We used The Cancer Genome Atlas and Gene Expression Profiling Interactive Analysis databases and investigated the association between the expression of ZDHHC15 and the anatomical distribution." (PMID 33541421, 2021). "To further corroborate the role of ZDHHC15 in regulating YAP transcription activity in cancer cells, we performed RNA sequencing analyses in ZDHHC15‐depleted and control cell lines (GEO accession numbers: GSE235254 and GSE235258)." (PMID 39686664, 2025). "Taken together, these findings strongly suggest that ZDHHC15 positively regulates YAP activity in cancer cells." (PMID 39686664, 2025). "We next sought to pharmacologically target the ZDHHC15‐YAP loop to suppress PA‐promoted cancer metastasis." (PMID 39686664, 2025). "Given that ZDHHC15 promotes YAP activity in cancer cells as revealed by our above findings, our data suggest that ZDHHC15 functions as a positive feedback mechanism to enhance YAP activity." (PMID 39686664, 2025). "Conversely, RGS20, RPH3A, SGCE, and ZDHHC15 exhibited a substantial downregulation in their expression levels within the corresponding cancer cell lines." (PMID 38300336, 2024). "Collectively, these data suggest that the ZDHHC15‐YAP loop is functional in cancer metastasis." (PMID 39686664, 2025). "We next sought to address whether the ZDHHC15‐YAP loop plays a role in PA‐promoted cancer metastasis." (PMID 39686664, 2025). "As we have shown that ZDHHC15 promotes YAP activity and forms a feedback loop with YAP in cancer cells, we next examined whether ZDHHC15 would influence tumor metastasis." (PMID 39686664, 2025). "We next examined the role of ZDHHC15 in PA‐mediated cancer metastasis." (PMID 39686664, 2025). "We further explored the palmitoyltransferase activity of ZDHHC15 in cancer metastasis in mice injected with MDA‐MB‐231 cells overexpressing ZDHHC15 WT or ZDHHC15 DHHS mutant and control cells (15 mice were randomly divided into 3 groups, n = 5 mice in each group)." (PMID 39686664, 2025). "Then, local anesthetics may also mediate the telomere homeostasis of cancer stem cells through ZDHHC15 or palmitoylation modification." (PMID 33541421, 2021). "In addition, YAP5SA but not YAP S94A could largely rescue these phenotypes upon ZDHHC15 depletion in the presence of PA, suggesting that ZDHHC15 functions in PA‐promoted cancer cell metastasis via YAP." (PMID 39686664, 2025). "We thus suggest a model in which PA drives the ZDHHC15‐YAP feedback loop regulating the Hippo/YAP pathway and cancer metastasis." (PMID 39686664, 2025). "Moreover, PA drives the ZDHHC15‐YAP loop, potentiating YAP activity and hence enhancing cancer metastasis." (PMID 39686664, 2025). "By performing brightfield lung imaging, H&E and IHC staining, determining body weight, counting the number of lung metastatic lesions, and calculating the survival rate, we showed that compared to ZDHHC15 WT, the DHHS mutant lost its ability to promote cancer metastasis." (PMID 39686664, 2025). "GSEA analysis of RNA‐seq (GEO accession number: GSE235258) performed in HCC1954 cells with or without ZDHHC15 silencing indicated that ZDHHC15 could impact cancer cell migration/invasion." (PMID 39686664, 2025). "Notably, YAP knockdown‐induced downregulation of the cell invasive capacity in HCC1954 or TOV‐112D cells could not be rescued by re‐expression of ZDHHC15 in these cells, suggesting that ZDHHC15 promotes cancer cell invasion upstream of YAP." (PMID 39686664, 2025).
tumor (3 papers, 2021 to 2025). "Collectively, these findings uncover a ZDHHC15‐YAP feedback loop as a previously unrecognized mechanism underlying PA‐promoted tumor metastasis and support targeting YAP and fatty acid synthesis as potential therapeutic targets in PA‐driven tumor metastasis." (PMID 39686664, 2025). "Single-cell functional analysis of tumors showed an association between ZDHHC15 and tumor cell proliferation and invasion." (PMID 37161425, 2023). "Collectively, our data provide novel insights into the underlying mechanisms by which PA promotes tumor metastasis, and suggest targeting the ZDHHC15‐YAP loop as a potential therapeutic strategy for mitigating PA‐mediated tumor metastasis." (PMID 39686664, 2025). "IHC analyses revealed a significantly increased staining for ZDHHC15 in tumor tissues relative to their paired non‐tumor tissues." (PMID 39686664, 2025). "H&E and IHC staining revealed decreased staining for CYR61, MMP‐2, and YAP in tumor sections from mice bearing the ZDHHC15‐depleted cells." (PMID 39686664, 2025). "Similar to the results observed with ZDHHC15 depletion, GSCs treated with local anesthetics before injection significantly suppressed tumor growth relative to control (or PBS-pretreated) animals." (PMID 33541421, 2021). "However, when mice were fed with a Palm‐diet, tumor sections from mice bearing ZDHHC15‐depleted cells showed more staining for KIBRA compared to the matched control cells." (PMID 39686664, 2025). "Targeting the ZDHHC15‐YAP loop may be a therapeutic strategy for mitigating PA‐mediated tumor metastasis." (PMID 39686664, 2025). "In addition, IHC staining showed that increased ZDHHC15 expression significantly correlated with both tumor grade (lower panel shows the quantification result) and distal metastasis." (PMID 39686664, 2025). "Given our findings that the ZDHHC15‐YAP loop is hijacked by PA in tumor metastasis, it represents an important vulnerability that may offer a window of therapeutic efficacy." (PMID 39686664, 2025). "Collectively, our study uncovers a ZDHHC15‐YAP feedback loop as a previously unrecognized mechanism underlying PA‐promoted tumor metastasis and underscores that PA serves as a signaling molecule driving the loop in tumor metastasis." (PMID 39686664, 2025). "Moreover, IHC analysis revealed reduced staining for ZDHHC15, MMP‐2, and CYR61in tumor sections from animals receiving ZDHHC15‐depleted tumor cells." (PMID 39686664, 2025). "In the tumor cell lines, ZDHHC15 has three isoforms, which are generated by alternative splicing." (PMID 33541421, 2021). "We further performed IHC analysis of tumor sections of mice bearing YAP‐depleted cells or control cells upon PA treatment and found that YAP depletion led to a markedly decreased staining for ZDHHC15." (PMID 39686664, 2025). "Notably, PA drives the ZDHHC15‐YAP feedback loop, thus enforces YAP signaling, and hence promotes tumor metastasis in murine xenografts." (PMID 39686664, 2025). "Furthermore, in each model, IHC staining of tumor sections from mice fed with a PA diet had increased staining for MMP‐2, YAP, and ZDHHC15 compared to mice fed with an Olive‐diet." (PMID 39686664, 2025).
infection (1 paper, 2022). The state of being infected such as from the introduction of a foreign agent such as serum, vaccine, antigenic substance or organism. "The stability ranking at different developmental stages associated with infection of PWN was as the following: TER > RPL7 > RPS5 > Zdhhc15 > EF1-γ > RPL18 > Tmub1 > SNX6 > ATPase > TFAM > α-TUB > EIF > TPI > COX7." (PMID 35547586, 2022). "For different treatments, TER, Zdhhc15 and EF1-γ had the most stable expression levels (average SD = 0.71, 0.73, 0.74, respectively) at different developmental stages associated with infection of PWN." (PMID 35547586, 2022).
ZDHHC15 also shares sentences with these, for which no sentence is quoted: anaplastic astrocytoma (1 paper); brain disorder (1); Breast and (1); cerebral palsy (1); cervical squamous cell carcinoma (1); cognitive disorder (1); endocervical adenocarcinoma (1); epilepsy (1); ovarian serous cystadenocarcinoma (1); pilocytic astrocytoma (1); psychiatric disorder (1); uterine corpus endometrial carcinoma (1).